EZH2 (enhancer of zeste 2 polycomb repressive complex 2 subunit)
Diseases named in the same sentence as EZH2 in open-access papers (continued):
Sharing a sentence is not in itself a finding about the gene and the disease.
oral squamous cell carcinoma (20 papers, 2010 to 2025). "EZH2 overexpression associated with tumor proliferation, lymph node metastasis, disease stage and poor prognosis of oral squamous cell carcinoma." (PMID 24345883, 2013). "In our previous study, we found that these two EZH2 SNPs (rs6950683 and rs3757441) might contribute to the prediction of oral squamous cell carcinoma (OSCC) susceptibility." (PMID 35813302, 2022). "We found that the inhibition of the CBP/β-catenin axis mediated by ICG-001 in oral squamous cell carcinoma led to the downregulation of BIRC5, EZH2, AURKA, CCNA2, and other genes previously implicated in therapy resistance." (PMID 41227355, 2025). "In the realm of targeted drug research, EZH2 shows great potential as a therapeutic target for oral squamous cell carcinoma." (PMID 38600608, 2024). "Actually, H19 silencing increased miR-138 expression and inhibited the proliferation, and invasion of oral squamous cell carcinoma cells in vitro and in vivo by reducing enhancer of zeste homolog 2 (EZH2) expression, which were attenuated by miR-138 silencing." (PMID 32272875, 2020). "HOTAIR, for instance, promotes tumor cell invasion and metastasis by recruiting EZH2 and repressing E-cadherin in oral squamous cell carcinoma." (PMID 29490660, 2018). "Association between proliferation by Ki-67 and expression of EZH2 has been shown in several other tumors such as prostate, breast, salivary gland adenoid cystic carcinoma, and oral squamous cell carcinoma." (PMID 20398247, 2010). "Inhibition of EZH2 could suppress oral squamous cell carcinoma (OSCC) progression via modulate EZH2/Wnt/beta-catenin pathway, both in vitro and in vivo." (PMID 39830511, 2024). "Interestingly, increased EZH2 expression has been reported in oral squamous cell carcinomas compared to dysplastic and normal epithelium." (PMID 26377323, 2015). "In oral squamous cell carcinoma, study showed that long non-coding RNA HOTAIR promotes tumor cell invasion and metastasis by recruiting EZH2 and repressing E-cadherin." (PMID 29050269, 2017). "Additionally, decreased expression of EZH2 significantly reduces migration and invasion rates in knocked-down OSCC (oral squamous cell carcinoma) cells." (PMID 38600608, 2024).
T-cell lymphoma (20 papers, 2015 to 2025). "Our further findings, along with those of others show that high EZH2 protein expression was associated with poor prognosis in T-cell lymphomas and markers that are known for cancer progression." (PMID 34944658, 2021). "This underlines the rationale for EZH2 targeting in T-cell lymphomas." (PMID 37297005, 2023). "Similarly, EZH2 overexpression in natural killer (NK)/T-cell lymphomas is associated with a growth advantage and poor prognosis." (PMID 26497210, 2016). "We have shown that pharmacological EZH2 inhibition can induce an increase in chemotherapy resistance, most prominent in oxaliplatin, which is commonly used as the second-line treatment of T-cell lymphomas." (PMID 37297005, 2023). "We have investigated EZH2 expression in two cohorts of T-cell lymphomas by mRNA-profiling and immunohistochemistry, both revealing overexpression to have a negative impact on patients’ prognosis." (PMID 37297005, 2023). "This gives a rationale to evaluate EZH2 inhibition as a potential new therapy of T-cell lymphomas, as a single agent but also in combination with cytotoxic agents, which is currently discussed." (PMID 37297005, 2023). "In order to clearly evaluate EZH2 dependence on the induction of oxaliplatin resistance in mature T-cell lymphomas, we established an EZH2 knockdown in HH." (PMID 37297005, 2023). "While EZH2 inhibitors show promising however moderate results as single agents in T-cell lymphomas as well as synergistic effects with other chemotherapeutics, our data do not support the combination with platinum derivates." (PMID 37297005, 2023). "As we and others have shown before, T-cell lymphomas overexpress EZH2, which is correlated to worse survival rates." (PMID 37297005, 2023). "This study demonstrates that pharmacological EZH2 inhibition can lead to an increase in chemotherapy resistance, here shown for oxaliplatin, a common second-line treatment drug in T-cell lymphomas." (PMID 37297005, 2023). "In this study, we evaluated the EZH1/2 mutation status in a cohort of 33 MEITL by NGS and investigated the immunohistochemical protein expression of EZH1, EZH2, and H3K27me3 in combination with the clinical outcomes in 46 patients with T-cell lymphomas." (PMID 34944658, 2021). "In fact, EZH2 was upregulated in natural killer/T-cell lymphoma, through Myc-mediated mRNA inhibition." (PMID 30510924, 2018). "This activity has been demonstrated especially in natural killer/T-cell lymphoma, in which cyclin D transcription is activated by EZH2 upregulation via Myc-mediated mRNA inhibition promoting cell proliferation without a methyltransferase activity." (PMID 30510924, 2018). "In fact, in natural killer/T-cell lymphoma, EZH2 upregulated via Myc-mediated mRNA inhibition, directly activates cyclin D transcription and promotes cell proliferation independently from methyltransferase activity." (PMID 26268310, 2015). "For example in natural killer/T-cell lymphoma, EZH2 upregulation directly activates cyclin D transcription via Myc-mediated mRNA inhibition and promotes cell proliferation independently from methyltransferase activity." (PMID 26268310, 2015). "Here, we analyzed EZH2 expression and its association with tumor proliferation and signaling cascade molecules in 43 ATLL cases and a total of 103 cases of other types of T-cell lymphomas, including T-ALL, ALCL-ALK+, ALCL-ALK−, NK/TCL, PTCL-NOS, AITL, and T-PLL." (PMID 38339397, 2024). "EZH2 exerts the PcI effect not only in endocrine-related cancers such as breast and prostate, but also in other aggressive cancers, such as the natural killer/T-cell lymphoma (NKTL)." (PMID 39769907, 2024). "Differently from this, the phosphorylation of EZH2 at Y646 residue by JAK2 promotes the β-TrCP-mediated EZH2 degradation and the phosphorylation on Y244 mediated by JAK3 suppresses PRC2 complex formation, resulting in EZH2 oncogenic function in natural killer/T-cell lymphoma." (PMID 39769907, 2024).
T-cell lymphoma (continued). "In the other T-cell lymphomas, there was variable co-expression of EZH2 with pERK, MYC, and pSTAT3." (PMID 38339397, 2024). "In an earlier study, we could show that mature T-cell lymphomas also showed EZH2 overexpression which impacts on patient outcomes." (PMID 37297005, 2023). "Consequently, EZH2 inhibition in T-cell lymphomas needs to be investigated thoroughly before being applied in clinical trials to rule out negative consequences." (PMID 37297005, 2023). "Thus, pharmacological EZH2 inhibition is a promising target and its clinical evaluation in T-cell lymphomas shows favorable results." (PMID 37297005, 2023). "Thus, we can conclude that EZH1 and EZH2 have the opposite impact on the OS in the T-cell lymphomas cohorts studied." (PMID 34944658, 2021). "Mutations of EZH1 and/or EZH2 are described as rare or absent in T-cell lymphomas by a number of groups." (PMID 34944658, 2021). "In addition, further mechanistic experiments are required to elucidate the molecular mechanisms of EZH1 and EZH2 in T-cell lymphomas." (PMID 34944658, 2021). "Moreover, compared with normal lymph node tissues, EZH2 and H3K27me3 proteins were found to be overexpressed in T-cell lymphomas, whereas EZH1 was underexpressed, which is consistent with previous reports." (PMID 34944658, 2021). "Targeting of both EZH1 and EZH2 enzyme activity may serve as a target for anticancer therapy in T-cell lymphomas." (PMID 34944658, 2021). "MiRNAs affect the expression of epigenetic modifying genes, and the downregulation of miR-101 and miR-128a may be responsible for increased EZH2 expression in T-cell lymphoma oncogenesis." (PMID 33160401, 2020). "Moreover, it was shown that, in natural killer/T-cell lymphoma (NKTL) models, phosphorylation of EZH2 at Y244 by JAK3 causes EZH2 dissociation from PRC2 and enhances its association with RNA Pol-II." (PMID 33327550, 2020). "The growth advantage associated with increased EZH2 expression in NK/T-cell lymphoma cells is independent of its H3K27 methylation activity." (PMID 26497210, 2016). "Overall, T-cell lymphomas show a heterogeneous and so far insufficiently characterized profile of EZH1, EZH2, and H3K27me3 expression as well as a poorly studied correlation of these proteins with each other and with clinicopathological markers." (PMID 34944658, 2021). "Despite the rapid development of new drugs inhibiting EZH2 and/or EZH1, the molecular interplay of these proteins and the impact on disease progression and prognosis of patients with T-cell lymphomas remains insufficiently understood." (PMID 34944658, 2021). "In the present study, we have revealed that pharmacological EZH2 inhibition is not suitable in combination with chemotherapeutic oxaliplatin which is commonly used in the second-line treatment of mature T-cell lymphomas." (PMID 37297005, 2023). "In conclusion, pharmacological EZH2 inhibition is not suitable in combination with the common chemotherapeutic oxaliplatin in T-cell lymphomas revealing an EZH2-independent off-target effect." (PMID 37297005, 2023). "Moreover, another study demonstrated that JAK3-mediated EZH2 tyrosine (Y) Y244 phosphorylation, which suppresses PRC2 complex formation, resulting in EZH2 oncogenic function independent of its HMTase activity in natural killer/T-cell lymphoma (NKTL)." (PMID 33308321, 2020). "During the sequential processes of PRC pathway activation and chromatin remodeling in T cell lymphomas, MALAT1 may directly and specifically bind to PRC pathway proteins, particularly EZH2 and SUZ12, members of the PRC2 family, which may in turn induce H3K27me3." (PMID 28412742, 2017). "Direct binding of MALAT1 to the PRC2 components (EZH2 and SUZ12) was observed in a T cell lymphoma cell line; however, no direct binding of MALAT1 with H3K27me3 and BMI1 (a PRC1 component) was observed." (PMID 28412742, 2017).
T-cell lymphoma (continued). "In the non-treated cell line derived from a patient with T cell lymphoma (HH cells), baseline protein expression levels of PRC-related markers, especially EZH2, SUZ12, BMI1, and H3K27me3, were very strong." (PMID 28412742, 2017).
squamous cell carcinoma (19 papers, 2011 to 2025). A carcinoma arising from squamous epithelial cells. "The 7 (of 37) thymic carcinomas with EZH2 staining in <80% of tumor cells included 2 (of 24, 8%) squamous cell carcinomas, 2 (of 2, 100%) mucoepidermoid carcinomas, 2 (of 2, 100%) adenocarcinomas, and 1 (of 3, 33%) undifferentiated carcinomas." (PMID 37190202, 2023). "Using the ≥80% threshold for EZH2 positivity, the two pathologists’ scores were concordant for all cases except for one squamous cell carcinoma and one type A thymoma (κ = 0.95, 95% CI 0.88–1, indicating excellent agreement)." (PMID 37190202, 2023). "In squamous cell carcinoma, enhancer of zeste homolog 2 (EZH2) inhibits RUNX3 (RUNX Family Transcription Factor 3) expression to activate both SETDB1 and ΔNp63α, which drives an aggressive cancer stem cell phenotype." (PMID 38057834, 2023). "The only prior study of EZH2 for thymic carcinoma versus thymoma used tissue microarrays to assess EZH2 in thymic squamous cell carcinomas (n = 27) and B3 thymomas (n = 26)." (PMID 37190202, 2023). "In an additional series consisting of 63 squamous cell carcinomas and 82 adenocarcinomas, significantly higher EZH2 expression was seen in squamous cell carcinomas in relation to adenocarcinomas." (PMID 33050946, 2020). "For instance, TFs such as SOX2 and NKX2‐1 are crucial in mediating the transformation of LUAD to squamous carcinoma, while epigenetic regulators like EZH2 and LSD1 influence tumour cell differentiation and proliferation by modulating histone modifications and DNA methylation." (PMID 40847555, 2025). "Previous studies showed an inverse correlation between EZH2 and MHC class I antigen presentation molecule expression levels in squamous cell carcinomas, such as head, neck, and lung squamous cell carcinoma." (PMID 33180829, 2020). "Looking broadly across all cancers, our results highlight that EZH2 is active in more primitive cancers of childhood, and HDAC4 is active in more mature adenocarcinomas and squamous cell carcinomas." (PMID 24079712, 2013). "Given that EZH2 inhibition appears to regulate both MHCI and class II in squamous cell carcinoma cells, this may help to delay or prevent acquired resistance that occurs more readily when only one molecular pathway is altered." (PMID 38265267, 2024). "Two of the five carcinomas negative for CD117 were positive for EZH2 using the ≥80% threshold (both squamous cell carcinomas), such that performing both EZH2 and CD117 IHC increased sensitivity from 86% (for CD117 alone) to 92%." (PMID 37190202, 2023).
acute lymphoblastic leukemia (18 papers, 2011 to 2025). Leukemia with an acute onset, characterized by the presence of lymphoblasts in the bone marrow and the peripheral blood. "In EZH2 deficient T cell acute lymphoblastic leukemia (T-ALL), a synthetic lethal screening identified Chk1 inhibition as an exploitable vulnerability." (PMID 40422251, 2025). "Loss of EZH2 in HSCs (hematopoietic stem cells) is sufficient to cause aggressive T-acute lymphoblastic leukemia (T-ALL) in mice." (PMID 27845897, 2017). "In contrast to GOF mutants, loss-of-function (LOF) mutants of EZH2 have also been identified in T-cell acute lymphoblastic leukemia (T-ALL)." (PMID 36076977, 2022). "Indeed, EZH2 or SUZ12 mutations are also observed in 25% of patients with T-cell acute lymphoblastic leukemia (T-ALL)." (PMID 26497210, 2016). "Only two germline EZH2 mutation-positive individuals developed hematological malignancies: E745K (a lymphoma diagnosed at the age of 13) and an A682T mutation (acute lymphoblastic leukemia (ALL) and neuroblastoma developed at 13 months)." (PMID 27239242, 2016). "However, there is disparate point of view that high level expression of EZH2 inhibits aggressive T-acute lymphoblastic leukemia, which means EZH2 can also act as a tumor suppressor." (PMID 27706111, 2016). "In some entities, like T cell Acute Lymphoblastic Leukemia (T-ALL) or lung adenocarcinoma, EZH2 fits the role of a tumor suppressor and is found deleted or inactivated by mutations." (PMID 34762160, 2022). "Loss-of-function mutations in EZH2 and SUZ12 also have been found in early T-cell precursor (ETP) acute lymphoblastic leukemia (ETP-ALL) and non-ETP T-ALL in children and T-ALL in adults." (PMID 33374737, 2020). "On the contrary, EZH2 inactivation correlates with increased growth and proliferation of stem-cells and early-progenitor-cells in early T cell precursor acute lymphoblastic leukemia (ETP-ALL), which represents an aggressive type of acute lymphoblastic leukemia." (PMID 27793053, 2016).
Burkitt lymphoma (18 papers, 2011 to 2025). A rare form of malignant mature B-cell non-Hodgkin lymphoma. "In conclusion, our study demonstrated that combining dEZH2 and aPD1 in Burkitt’s lymphoma counteracted immune evasion caused by EZH2 inhibition-induced PD-L1 upregulation, leading to significantly enhanced apoptosis both in vitro and in vivo." (PMID 40308579, 2025). "Our study focuses on evaluating the combined efficacy of EZH2 inhibition and the immune checkpoint inhibitor anti-PD-1 specifically in cytotoxic T lymphocytes co-cultured Burkitt’s lymphoma." (PMID 40308579, 2025). "It has been reported that by repressing miR-26a, MYC stimulates EZH2 expression in Burkitt lymphoma cells, highlighting how EZH2 deregulation is interconnected with c-MYC-driven tumorigenesis." (PMID 39769907, 2024). "In conclusion, iEZH2 treatment was ineffective in Burkitt’s lymphoma, despite the importance of EZH2 in the disease." (PMID 37752998, 2023). "Leveraging the relevance of this pathway, we conducted drug combination experiments involving an HER2 inhibitor and EZH2 degrader in our Burkitt’s lymphoma cell line with EBV oncoprotein." (PMID 37760442, 2023). "DZnep effectively depletes cellular levels of EZH2, inhibits tri-methylation of Histone H3 at lysine 27, and induces cell apoptosis in a variety of cancerous contexts, including Burkitt lymphoma, ALL, and NKTL." (PMID 31752930, 2019). "We prepared and analyzed the EZH2-KO cell lines derived from an EBV-negative Burkitt lymphoma B cell line, Akata(−)." (PMID 30487153, 2018). "Based on our findings, we propose that the combination of an EZH2 degrader and anti-PD-1 therapy may serve as an effective treatment strategy for patients with Burkitt’s lymphoma." (PMID 40308579, 2025). "Next, we investigated the role of EZH2 inhibition in immune evasion in Burkitt’s lymphoma." (PMID 40308579, 2025). "These suggest that in the treatment of Burkitt lymphoma through EZH2 degradation, tumor cells could evade immune responses mediated by CTLs to enhance their survival." (PMID 40308579, 2025). "Burkitt’s lymphoma is also characterized by the overexpression of EZH2." (PMID 40308579, 2025). "Therefore, targeting EZH2 represents a potential therapeutic strategy for treating Burkitt’s lymphoma." (PMID 40308579, 2025). "Based on these findings, we hypothesized that in order to enhance the therapeutic efficacy of EZH2 inhibition in Burkitt’s lymphoma within an immune cell-rich environment, it is crucial to limit the activity of PD-L1 using anti-PD-1 (aPD1) treatment." (PMID 40308579, 2025). "To further investigate whether the inhibition of EZH2 induces cell death in Burkitt’s lymphoma, we performed flow cytometry using Annexin V/PI staining." (PMID 40308579, 2025). "Next, we performed a western blot analysis to confirm whether iEZH2 and dEZH2 actually reduce EZH2 expression levels in Burkitt’s lymphoma cells." (PMID 40308579, 2025). "Therefore, we will investigate the impact of EZH2 on the survival of Burkitt’s lymphoma using Tazemetostat and MS1943." (PMID 40308579, 2025). "In addition, our study focused on investigating the potential therapeutic efficacy of simultaneous targets of EZH2 and BTK in Burkitt’s lymphoma and exploring the underlying apoptotic pathways associated with this drug combination." (PMID 37752998, 2023). "In addition, missense EZH2 point mutations were also identified in a few Burkitt lymphoma cases with functions not fully determined." (PMID 31752930, 2019). "In an in vivo study, the liver of hu-PBMC-CDX mouse showed less tumor cell infiltration compared to the control, along with decreased expression levels of EZH2 and c-MYC, indicating that dEZH2 effectively suppresses Burkitt’s lymphoma." (PMID 40308579, 2025). "In this study, we investigated the inhibitory effects of two drugs, the FDA-approved EZH2 inhibitor Tazemetostat, currently undergoing clinical trials, and the novel drug MS1943, on Burkitt’s lymphoma." (PMID 37752998, 2023).